PLSCR4 (phospholipid scramblase 4)
Description:
Catalyzes metal ion-induced ATP-independent rapid bidirectional and non-specific movement of phospholipids (lipid scrambling or lipid flip-flop) between the inner and outer leaflet of the plasma membrane and participates in the redistribution of phospholipids between membrane leaflets. Metal ions bind to the calcium-binding site and induce conformation change in the protein. Has a greater affi nity for Ca(2+) than Mg(2+) and Zn(2+).
Synonyms: TRA1
Tractability: Antibody: UniProt places it where antibodies can reach, with high confidence; its Gene Ontology location is reachable by antibodies, with high confidence; UniProt predicts a signal peptide or a membrane-spanning region. PROTAC: its protein half-life has been measured.
Gene: Protein-coding gene on chromosome 3 (146,192,335 to 146,251,179, reverse strand). Ensembl gene ENSG00000114698.
Subcellular location: Cell membrane; Nucleus
Subcellular location (Human Protein Atlas): Nuclear bodies; Nucleoplasm
Gene Ontology:
Molecular function: CD4 receptor binding; enzyme binding; phospholipid scramblase activity; protein binding; calcium ion binding
Biological process: calcium activated phosphatidylcholine scrambling; calcium activated phosphatidylserine scrambling; plasma membrane phospholipid scrambling; cellular response to lipopolysaccharide
Cellular component: nucleus; plasma membrane
Genetic constraint (gnomAD): Loss-of-function variants: 10 observed, 23.95 expected, observed/expected ratio (o/e) 0.42, 90% interval 0.26 to 0.71. The upper end of that interval is the gene's LOEUF score, 0.71, which puts it in group 2 of 6, group 1 being the genes least tolerant of losing a copy. Missense variants: 336 observed, 360.82 expected, observed/expected ratio (o/e) 0.93, 90% interval 0.85 to 1.02. Synonymous variants: 105 observed, 119.88 expected, observed/expected ratio (o/e) 0.88, 90% interval 0.75 to 1.03.
Homologues: Orthologues: chimpanzee PLSCR4 (99% identical), macaque PLSCR4 (92% identical), rabbit PLSCR4 (86% identical), dog PLSCR4 (84% identical), guinea pig PLSCR4 (83% identical), pig PLSCR4 (81% identical), rat Plscr4 (81% identical), mouse Plscr4 (79% identical), zebrafish plscr3b (41% identical), zebrafish si:ch211-71m22.1 (34% identical), zebrafish si:dkey-62k3.6 (33% identical), zebrafish si:ch211-71m22.5 (33% identical), and 13 more. Paralogues in human: PLSCR1 (45% identical), PLSCR3 (35% identical), PLSCR2 (34% identical), PLSCR5 (33% identical).
Diseases named in the same sentence as PLSCR4 in open-access papers:
PLSCR4 is named in the same sentence as 24 diseases in open-access papers, as found by Europe PMC text mining. Sharing a sentence is not in itself a finding about the gene and the disease. The quoted sentences say what the papers report.
cardiac hypertrophy (4 papers, 2019 to 2025). "In TAC-operated mice model, lncRNA Plscr4 forced expression was indicated to attenuate cardiac hypertrophy by sponging miR-214 and further upregulating mitofusin 2 (Mfn2) expression, a critical modulator of mitochondrial homeostasis." (PMID 31355277, 2019). "The lncRNA Plscr4 blocks the development of cardiac hypertrophy by targeting the miR-214/Mfn2 axis." (PMID 40874024, 2025). "In our previous study, we found that LncRNA Plscr4 could act as a sponge for miR-214 and mediate the expression of Mfn2 to influence mitochondrial function and regulate the development of cardiac hypertrophy." (PMID 37253771, 2023).
schizophrenia (3 papers, 2007 to 2023). A major psychotic disorder characterized by abnormalities in the perception or expression of reality. "Of these, Plscr4, Armc8, Zbtb38, Rbp1, Zic1, and Trpc1 have been linked to schizophrenia or schizophrenia-related disorders in previous studies." (PMID 31920576, 2019). "Moreover, the PLSCR4 gene, as a target of miRNA 16-5p, has been verified to associate with schizophrenia in previous studies." (PMID 37816766, 2023). "For schizophrenia, but not bipolar disorder, the differential expression of PLSCR4 and EMX2 was confirmed by RT-PCR." (PMID 17997842, 2007). "Two novel candidate genes, PLSCR4 and EMX2, were confirmed as differentially expressed in schizophrenia between suicide completers vs. non-suicide groups." (PMID 17997842, 2007).
breast carcinoma (2 papers, 2016 to 2020). "PLSCR4 encodes phospholipid scramblase 4, a transmembrane Ca2+ binding protein; the function of ions in relation to breast cancer has been widely discussed and it has been suggested lower levels of intracellular calcium may be preventing cell death." (PMID 27341628, 2016).
non-small cell lung carcinoma (2 papers, 2014 to 2021). A group of at least three distinct histological types of lung cancer, including non-small cell squamous cell carcinoma, adenocarcinoma, and large cell carcinoma. "Linc00641 repressed cell proliferation and induced apoptosis in non-small cell lung cancer (NSCLC) cells by sponging miR-424-5p to increase the expression of phospholipid scramblase (PLSCR4)." (PMID 33714199, 2021).
dyslipidemia (1 paper, 2022). "Since Plscr3 knockout mice showed a higher accumulation of abdominal fat as well as insulin resistance, glucose intolerance, and dyslipidemia, we aimed to investigate the role of PLSCR4 in other models of lipid accumulation." (PMID 36077184, 2022).
lipoma (1 paper, 2022). A benign, usually painless, well-circumscribed lipomatous tumor composed of adipose tissue. "The present study was designed to investigate the role of PLSCR4 in adipose progenitor proliferation and differentiation in order to better understand the molecular causes of lipoma development in patients with PHTS." (PMID 36077184, 2022). "In lipoma tissue from a mouse model of PTEN deficiency, we observed a lower expression of PLSCR4 compared with control adipose tissue, proposing a contribution of PLSCR4 downregulation to the adipose-tissue overgrowth observed in patients with PHTS." (PMID 36077184, 2022). "We observed decreases in Plscr4 expression of 67.7% ± 15.4% in lipoma Pten/Rb DKO tissue compared with epiWAT (n = 7; p = 0.0019) and of 58.4% ± 23.5% compared with ingWAT (n = 7; p = 0.0318)." (PMID 36077184, 2022). "In this study, we analyzed the role of a potentially involved factor, PLSCR4, in adipose tissue and its impact on lipoma formation in PHTS patients." (PMID 36077184, 2022). "We observed that PLSCR4 expression was downregulated in lipoma tissue from conditional Pten/Rb double knockout mice in comparison with epididymal and inguinal WAT of control mice." (PMID 36077184, 2022). "We compared Plscr4 gene expression in lipoma tissue from Pten/Rb DKO with inguinal (ing) and epididymal (epi) white adipose tissue (WAT) from Cre negative-control mice." (PMID 36077184, 2022). "We used an APC strain termed LipPD1 established from the lipoma tissue of a patient with a germline mutation in the PTEN gene and APCs from obese but otherwise healthy individuals to investigate PLSCR4 expression during adipocyte differentiation." (PMID 36077184, 2022). "To investigate a potential functional role of PLSCR4 in adipocyte development and lipoma formation, we knocked down or overexpressed PLSCR4 in APCs and examined the changes in proliferation and adipocyte differentiation compared with controls." (PMID 36077184, 2022). "Similarly, during the adipogenesis of lipoma cells from a patient with PHTS, we observed a downregulation of PLSCR4 at the mRNA and protein levels, suggesting an association of reduced PLSCR4 with adipocyte differentiation." (PMID 36077184, 2022). "Our results indicated that PLSCR4 is a regulator of PI3K/AKT signaling and adipogenesis and may play a role in PTEN-associated adipose-tissue overgrowth and lipoma formation." (PMID 36077184, 2022).
lung carcinoma (1 paper, 2022). "Four of the five genes (HEG1, PLSCR4, GMFG, and NME4) associated with LC-BC alignments have been observed to be deregulated in lung cancer." (PMID 36101460, 2022).
rectal cancer (1 paper, 2021). A primary or metastatic malignant neoplasm that affects the rectum. "After knocking down miRNA-424-5p in rectal cancer cells, PLSCR4 expression was up-regulated, and PLSCR4 was positively correlated with LINC00641." (PMID 35155216, 2021). "LINC00641 plays a carcinogenic role in rectal cancer through miRNA-424-5p/PLSCR4 axis, which can provide a new target for the treatment of rectal cancer." (PMID 35155216, 2021).
renal carcinoma (1 paper, 2022). A carcinoma arising from the epithelium of the renal parenchyma or the renal pelvis. "In contrast, high expression of FRZB, MYBL2, MYL2, NETO2, PLSCR4, and TES predicts an unfavorable outcome in endometrial, head and neck, liver, pancreatic, and renal cancer." (PMID 36497479, 2022).
cancer (5 papers, 2017 to 2025). A tumor composed of atypical neoplastic, often pleomorphic cells that invade other tissues. "ReactomeFIViz enrichment analysis in Cytoscape showed that two genes (HEG1 and PLSCR4) have evidence of their association with the acquisition of cancer characteristics." (PMID 36101460, 2022). "All the 12 other genes that have been identified with FLRT2 in silico to be hypermethylated in cancer also showed downregulation in MDA-MB-231 compared to in MCF-10A except for PLSCR4." (PMID 28325946, 2017). "Furthermore, an analysis of the relationship between infiltration estimation and gene expression in gene modules revealed that T-cell CD4+ Th1 in genes ERRFI1, ZBED5, UQCRC2, ZNF146, ABHD17A, YWHAZ, and especially PLSCR4 showed a negative correlation in nearly 40 types of cancer." (PMID 38464509, 2024).
PLSCR4 also shares sentences with these, for which no sentence is quoted: bipolar disorder (1 paper); brain tumors (1); colorectal cancer (1); Glucose intolerance (1); HIV-1 infection (1); Insulin resistance (1); liver cancer (1); malignant glioma (1); malignant melanomas (1); Obesity (1); osteosarcoma (1); protein misfolding disorders (1); respiratory diseases (1); tumor (1).